DPP7 (dipeptidyl peptidase 7)
Description:
Plays an important role in the degradation of some oligopeptides.
Synonyms: DPP II; DPP2; QPP; DPPII; DPP; II
Tractability: Small molecule: a high-quality ligand is known; it has a high-quality binding pocket; it belongs to a druggable protein family. Antibody: UniProt places it where antibodies can reach, with high confidence; its Gene Ontology location is reachable by antibodies, with high confidence; UniProt predicts a signal peptide or a membrane-spanning region. PROTAC: ubiquitination databases record sites on it; its protein half-life has been measured; a small molecule that binds it is known.
Target class: Enzyme; Serine protease S28 family; Serine protease SC clan; Protease; Serine protease
Gene: Protein-coding gene on chromosome 9 (137,110,540 to 137,118,309, reverse strand). Ensembl gene ENSG00000176978.
Subcellular location: Lysosome; Cytoplasmic vesicle; Secreted
Subcellular location (Human Protein Atlas): Vesicles; Golgi apparatus; Predicted to be secreted
Pathways (Reactome):
Immune System: Neutrophil degranulation
Gene Ontology:
Molecular function: serine-type peptidase activity; dipeptidyl-peptidase activity; peptidase activity; serine-type exopeptidase activity
Biological process: protein catabolic process; proteolysis
Cellular component: extracellular exosome; vesicle; azurophil granule lumen; extracellular region; lysosome; cytoplasmic vesicle
Genetic constraint (gnomAD): Loss-of-function variants: 74 observed, 52.54 expected, observed/expected ratio (o/e) 1.41, 90% interval 1.17 to 1.71. The synonymous counts are far from expectation, so gnomAD's model fits this gene poorly and the ratio says little. Missense variants: 805 observed, 648.12 expected, observed/expected ratio (o/e) 1.24, 90% interval 1.17 to 1.32. Synonymous variants: 350 observed, 278.53 expected, observed/expected ratio (o/e) 1.26, 90% interval 1.15 to 1.37.
Homologues: Orthologues: chimpanzee DPP7 (99% identical), macaque DPP7 (86% identical), mouse Dpp7 (79% identical), rat Dpp7 (78% identical), pig DPP7 (77% identical), dog DPP7 (76% identical), guinea pig DPP7 (74% identical), zebrafish dpp7 (53% identical), Caenorhabditis elegans K12H4.7 (23% identical), Drosophila melanogaster CG11626 (21% identical), Drosophila melanogaster CG18493 (20% identical), Drosophila melanogaster CG3734 (20% identical), and 1 more. Paralogues in human: PRCP (41% identical), PRSS16 (27% identical).
Diseases named in the same sentence as DPP7 in open-access papers:
DPP7 is named in the same sentence as 34 diseases in open-access papers, as found by Europe PMC text mining. Sharing a sentence is not in itself a finding about the gene and the disease. The quoted sentences say what the papers report.
colorectal cancer (7 papers, 2021 to 2025). A primary or metastatic malignant neoplasm that affects the colon or rectum. "This suggests that DPP7 plays a pivotal role in the progression of colorectal cancer, which underlines the therapeutic potential of Tamarixetin by inhibiting DPP7." (PMID 40845164, 2025). "Therefore, DPP7 is aberrantly overexpressed in colorectal tumors and is closely associated with the poor prognosis of patients with colorectal cancer." (PMID 37568770, 2023). "We first analyzed the diagnostic value of DPP7 in colorectal cancer patients." (PMID 37568770, 2023). "In this study, we identified DPP7 as a novel regulator of disulfidptosis and immune evasion in colorectal cancer through its interaction with GPX4." (PMID 40576169, 2025). "It has been found that overexpression of DPP7 counteracts the suppressive effect of Tamarixetin on colorectal cancer." (PMID 40845164, 2025). "In conclusion, our study identifies DPP7 as a novel regulator of disulfidptosis and immune evasion in colorectal cancer through its interaction with GPX4." (PMID 40576169, 2025). "Our analysis of the TCGA‐COAD dataset showed that DPP7 is significantly overexpressed in colorectal cancer tissues compared to adjacent normal tissues, and its high expression is associated with poor overall and progression‐free survival." (PMID 40576169, 2025). "In this study, we aimed to investigate the role of DPP7 in colorectal cancer progression and its potential involvement in regulating disulfidptosis and immune evasion." (PMID 40576169, 2025). "Immunohistochemistry analysis revealed a marked increase in DPP7 expression in colorectal cancer tissues compared to normal colorectal epithelium." (PMID 39247602, 2024). "In vitro cell experiments demonstrated that overexpression of DPP7 enhances the proliferation, invasion, and migration of colorectal cancer cells, while knockdown of DPP7 expression can inhibit tumor cell proliferation, invasion, and migration." (PMID 39247602, 2024). "The results of this study indicate that DPP7 is upregulated in various malignant tumors, including colorectal cancer." (PMID 39247602, 2024). "DPP7 is a potential prognostic biomarker for colorectal cancer, and overexpression of DPP7 in colorectal tumors can increase the malignant potential of the tumor and promote immune evasion." (PMID 39247602, 2024). "Cell experiments demonstrate that overexpression of DPP7 enhances the proliferation, migration, and invasion capabilities of colorectal cancer cells both in vitro and in vivo." (PMID 39247602, 2024). "Nevertheless, this study has revealed the inhibitory effect of overexpressed DPP7 on immune cell function in the colorectal cancer immune microenvironment for the first time, providing insights for future development of anti-colorectal cancer drugs." (PMID 39247602, 2024). "To further investigate the expression level in human colorectal cancer, we used qPCR to detect the expression level of DPP7 in colorectal tumor tissues and their paired adjacent normal tissues at the mRNA level." (PMID 37568770, 2023). "Second, we need to carry out further studies on cell lines and animal models to elucidate the biological function and mechanism of DPP7 in colorectal cancer cells." (PMID 37568770, 2023). "Furthermore, an inhibitor of the Wnt pathway showed to be lethal for colorectal cancer cells overexpressing DPP7." (PMID 40845164, 2025). "This study focuses specifically on the role of DPP7 in colorectal cancer." (PMID 40845164, 2025). "Conversely, dipeptidyl peptidase 7 (DPP7) promotes colorectal cancer progression by binding glutathione peroxidase 4 (GPX4), stabilising this redox guardian to suppress cytoskeletal disulfide aggregation (e.g., in drebrin, FLNA/B) and evade NK cell cytotoxicity." (PMID 40790550, 2025).
colorectal cancer (continued). "This may be because high expression of DPP7 by colorectal cancer cells invading lymph nodes severely disrupts the transmission of antigen recognition by immune cells in lymph nodes, leading to immune deficiency in tumors and poorer prognosis for patients." (PMID 39247602, 2024). "In summary, elevated expression of DPP7 in colorectal cancer promotes tumor cell proliferation, migration, and invasion on the one hand and mediates immune escape of colorectal cancer by interfering with the immune function of macrophages and Jurkat cells on the other hand." (PMID 39247602, 2024). "Based on these research findings, this study hypothesizes that DPP7 plays a crucial role in the malignant progression of colorectal cancer." (PMID 39247602, 2024). "The aberrant upregulation of DPP7 expression could enhance tumor malignancy and promote immune evasion in colorectal cancer." (PMID 39247602, 2024). "In summary, our findings lead us to conclude that DPP7 may be a potential prognostic biomarker for colorectal cancer." (PMID 39247602, 2024). "Furthermore, immunoblotting experiments revealed that DPP7 affects the expression of EMT-related proteins in colorectal cancer cells, potentially playing an important role in promoting the EMT process of colorectal cancer cells." (PMID 39247602, 2024). "The regulative mechanism of DPP7 in colorectal cancer cells deserves further investigation." (PMID 37568770, 2023). "DPP7 had high expression levels in colorectal cancer patients and could be a significant predictor of a poor prognosis; this is also consistent with our Oncomine and GEPIA analyses." (PMID 34359286, 2021). "Furthermore, the downregulation of DPP7 expression inhibits tumor formation in colorectal cancer." (PMID 39247602, 2024). "However, our immune infiltration analysis found a positive correlation between Tregs and DPP7 expression, suggesting that Tregs in the tumor immune microenvironment of colorectal cancer patients may promote tumor progression by inhibiting immune cell function." (PMID 39247602, 2024). "We examined DPP7 expression in various colorectal cancer (CRC) cell lines and found that HCT116 and SW480 cells expressed notably higher levels of DPP7." (PMID 40576169, 2025). "Thus, DCs associated with high DPP7 expression in colorectal cancer may not promote immunity as expected; instead, they may promote tumor progression similar to the action of Treg cells." (PMID 39247602, 2024). "Targeting DPP7 and/or its interaction with GPX4 may represent a novel strategy to enhance the efficacy of immunotherapy in colorectal cancer." (PMID 40576169, 2025). "We found that the expression level of DPP7 in CRC samples was significantly higher than that in adjacent non-tumor tissues by analyzing public colorectal cancer data and surgical specimens of CRC patients." (PMID 37568770, 2023).
breast carcinoma (6 papers, 2020 to 2024). "DPP7 is a member of the dipeptidyl peptidase family of proteins, which is highly expressed in breast cancer and is associated with a better prognosis." (PMID 38168553, 2024). "However, a recent study found that a high expression level of DPP7 was associated with a good prognosis in breast cancer." (PMID 37568770, 2023). "However, bioinformatic research has found that high DPP7 expression levels are associated with a better prognosis in breast cancer patients, suggesting that DPP7 may function in a tissue-specific manner in different cancers." (PMID 39247602, 2024). "High expression levels of DPP3 and DPP4 were associated with poor survival of breast cancer patients, whereas high expression levels of DPP6, DPP7, DPP8, and DPP9 were associated with good prognoses." (PMID 34359286, 2021). "DPP7 is a member of dipeptidyl peptidase (DPP) family, a high expression of which was related to a favorable prognosis in breast cancer." (PMID 37377935, 2023). "Data demonstrated that DPP3, DPP7, DPP8, DPP9, and DPP10 mostly had medium protein expression levels, while some clinical tissues showed strong positive expression levels of DPP3, DPP7, and DPP9 in breast cancer specimens." (PMID 34359286, 2021). "We found that DDP7 was highly expressed in colon cancer tissues but not in breast cancer patients; therefore, the role of DPP7 in cancer progression may occur in a tissue-specific manner." (PMID 34359286, 2021). "This family comprises seven members, including DPP3, DPP4, DPP6, DPP7, DPP8, DPP9, and DPP10; however, information on the involvement of DPPs in breast cancer is lacking in the literature." (PMID 34359286, 2021).
chronic lymphocytic leukemia (3 papers, 2019 to 2024). "Studies have shown that individuals with higher DPP7 activity typically exhibit a poorer prognosis in chronic lymphocytic leukemia (CLL) patients." (PMID 39247602, 2024). "Inhibition of DPP7 leads to apoptosis of the majority of resting cells in chronic lymphocytic leukemia." (PMID 33810334, 2021).
colon cancer (3 papers, 2021 to 2024). "Both the mRNA and protein levels of DPP7 were significantly higher in the colon cancer samples than in the normal tissues." (PMID 37568770, 2023). "After verifying the differential expression of DPP7 in the colon cancer and adjacent tissues, we further analyzed the prognostic and diagnostic value of DPP7." (PMID 37568770, 2023). "In addition, using the CbioPortal and TCGA database, a high mRNA expression of DPP7 was observed in 5% of the colon cancer samples." (PMID 37568770, 2023). "The expression of DPP7 exhibited a negative correlation with the efficacy of several drugs, such as fluorouracil, dabrafenib, and selumetinib, frequently prescribed for colon cancer." (PMID 37568770, 2023).
colon adenocarcinoma (2 papers, 2024 to 2025). "Yet, there is prognostic significance to DPP7; it is shown that higher DPP7 expression is correlated to a higher patient survival rate in the presence of colon adenocarcinomas, and that DPP7 is significantly under-expressed in tumor tissue." (PMID 38732562, 2024). "Analysis of The Cancer Genome Atlas Colon Adenocarcinoma (TCGA‐COAD) dataset revealed that patients with high DPP7 expression had significantly poorer overall survival (p = 0.0001) and progression‐free survival (p = 0.0011) compared to those with low DPP7 expression." (PMID 40576169, 2025).
colorectal tumor (2 papers, 2023 to 2024). "Consistent with the results from the bioinformatic analysis, the level of DPP7 in colorectal tumors was significantly higher than that in adjacent non-tumor tissues." (PMID 37568770, 2023).
COVID-19 (2 papers, 2021 to 2022). A disease caused by infection with severe acute respiratory syndrome coronavirus 2. "In random forest models for COVID-19, CST5, DPP7, NADK, KYAT1 and TYMP showed the highest variable importance." (PMID 35967328, 2022).
diabetes (2 papers, 2021 to 2024). "Recent studies also indicate that DPP4 and DPP7 directly link between periodontal and systemic diseases, such as type 2 diabetes mellitus and coagulation abnormality, respectively." (PMID 33006264, 2021). "DPP7 belongs to the proline-specific dipeptidyl peptidases (DPPs) family, which significantly influence the modulation of peptide hormone signaling and participate in metabolic processes pertinent to diabetes, oncology, and hematology." (PMID 39411310, 2024).
rectal cancer (2 papers, 2023 to 2024). A primary or metastatic malignant neoplasm that affects the rectum. "The analysis revealed that patients with high DPP7 expression had worse prognosis in both colon and rectal cancer patients with lymph node metastasis." (PMID 39247602, 2024). "The subgroup analyses of colon or rectal cancer also confirmed that patients with high DPP7 expression had a worse prognosis." (PMID 37568770, 2023).
steatosis (2 papers, 2021 to 2023). Increased lipid within the cytoplasm of cells. "Two circulating proteins Sialic Acid Binding Ig-Like Lectin 7 (SIGLETC7) and Dipeptidyl Peptidase 7 (DPP7), also showed significant differences according to the degree of steatosis." (PMID 38034016, 2023). "Importantly, we found that a subset of those proteins, CTSB, LIPA, DPP7, and GLMP had been previously connected with liver fibrosis, liver damage, and steatosis." (PMID 34440927, 2021). "Importantly, we found that lysosomal DEPs, including CTSB/D/Z, LIPA, DPP7 and GLMP, and mitocondrial DEPs, AKR1B10, and VAT1 had been connected with liver fibrosis, damage, and steatosis in previous studies, validiting our dataset." (PMID 34440927, 2021).
bladder cancer (1 paper, 2019). "As the expression of DPP7/2 is downregulated in CRC tumor tissues, it shows inverse correlation with PCMT1, which has been shown to express at higher amounts in bladder cancer." (PMID 31387239, 2019).
intestinal cancer (1 paper, 2024). "Likewise, DPP7′s potential role in intestinal cancer has not been widely noted." (PMID 38732562, 2024).
liver cancer (1 paper, 2024). An epithelial or non-epithelial malignant neoplasm that arises from the liver. "Furthermore, studies have indicated that in hepatitis B virus-infected liver cancer cells, DPP7 expression levels increase, and the integration of the hepatitis B virus with DPP7 is closely related to the process of cell apoptosis." (PMID 39247602, 2024).
lymph node metastasis (1 paper, 2024). "Prognostic data analysis indicated poorer prognosis in patients with lymph node metastasis and high DPP7 expression." (PMID 39247602, 2024). "Our analysis of patient prognosis revealed that patients with high DPP7 expression had poorer prognosis in the presence of lymph node metastasis." (PMID 39247602, 2024). "Further analysis of TCGA data and immunohistochemistry results revealed that patients with lymph node metastasis had higher DPP7 expression at transcriptional and protein levels than those without lymph node metastasis." (PMID 39247602, 2024). "Previous analyses indicated that patients with lymph node metastasis had higher DPP7 expression than those without metastasis." (PMID 39247602, 2024).
metastatic disease (1 paper, 2023). "An advanced T stage, N stage, individuals older than 65 years, a high level of CEA (>5 ng/mL), residual tumor or metastatic disease, lymphatic invasion, and high DPP7 expression were significantly associated with worse OS in the univariate analysis." (PMID 37568770, 2023).
Sepsis (1 paper, 2025). Sepsis is defined as life-threatening organ dysfunction caused by a dysregulated host response to infection. "In conclusion, our study indicates the potential importance of key genes including CDC25B, DPP7, FBXO31, and PTCD3 in the shared pathogenesis of sepsis and T2DM." (PMID 41194984, 2025). "Differential gene expression and co-expression network analyses identified five key genes—CDC25B, DPP7, FBXO31, PTCD3, and CNPY2—that play critical roles in immune response and cellular regulation in sepsis and T2DM." (PMID 41194984, 2025). "Further refinement by intersecting these genes with previously identified DEGs yielded five candidate genes: CDC25B, DPP7, FBXO31, PTCD3, and CNPY2, These genes emerged as promising biomarkers for both T2DM and sepsis, warranting further investigation into their functional roles." (PMID 41194984, 2025). "In our study, DPP7 expression positively correlated with immune activation markers (e.g., T-cell co-stimulation, HLA expression) and negatively with immunosuppressive factors (e.g., Tregs, APC co-inhibition), suggesting a dual role in immune regulation during sepsis and T2DM." (PMID 41194984, 2025).